GAS5 (growth arrest specific 5)
Diseases named in the same sentence as GAS5 in open-access papers (continued):
Sharing a sentence is not in itself a finding about the gene and the disease.
gastric cancer (64 papers, 2014 to 2026). A primary or metastatic malignant neoplasm involving the stomach. "They demonstrated if gastric cancer patients had allele deletion they displayed higher GAS5 expression in their cancer tissue samples." (PMID 32547314, 2020). "Another study has demonstrated that lncRNA GAS5 rs145204276 was significantly associated with a reduced risk of gastric cancer." (PMID 33119060, 2020). "Many studies have demonstrated that carriers of GAS5 rs145204276 have an increased risk of various types of cancer, including gastric cancer and HCC." (PMID 32354045, 2020). "The expression level of growth arrest-specific transcript 5 (GAS5) lncRNA is significantly down-regulated in gastric cancer tissues, and its reduction is associated with cancer cell migration and invasion." (PMID 29721215, 2018). "A study suggested that Gas5 expression was significantly lower in gastric cancer tissues compared to normal tissues, and Gas5 with lower expression was associated with larger tumor diameter and a more advanced clinical stage of gastric cancer." (PMID 29308053, 2018). "GAS5 has already been reported to be associated with the occurrence of gastric cancer, and HOTAIR has also been reported on by us." (PMID 28077118, 2017). "Our analysis missed some lncRNAs that have reported to be associated with overall survival of gastric cancer patients, such as GAS5 and HOTAIR." (PMID 28841672, 2017). "Taken together, these data indicate that low GAS5 expression level is an independent risk factor for gastric cancer patients." (PMID 24884417, 2014). "We found that GAS5 expression was markedly downregulated in gastric cancer tissues, and associated with larger tumor size and advanced pathologic stage." (PMID 24884417, 2014). "Further well understanding of the mechanisms of GAS5 in the molecular etiology of gastric cancer will promote the development of lncRNA-directed diagnostic and therapeutic agents against this deadly disease." (PMID 24884417, 2014). "The overexpression of GAS5 can inhibit the proliferation of gastric cancer cells, and a higher GAS5 level may cause the retardation of tumor angiogenesis." (PMID 33925911, 2021). "Overexpression of GAS5 is strongly associated with the suppression of tumor growth and development, because it suppresses miRNA-106a-5p expression through the mammalian target of the rapamycin (mTOR) pathway in gastric cancer." (PMID 32354045, 2020). "In addition, some scholars have studied the role of GAS5 gene variant rs145204276 in gastric cancer cells." (PMID 30606744, 2019). "In summary, we demonstrate that the decreased GAS5 expression is a common event underlying gastric cancer, indicating that GAS5 may play a key tumor-suppressive as an indicator of poor survival rate and a negative prognostic factor for gastric cancer patients." (PMID 24884417, 2014). "Numerous articles have shown that GAS5 can control the proliferation of Adriamycin-resistant gastric cancer cell lines." (PMID 38927012, 2024). "For instance, the lncRNA GAS5 inhibits progression of gastric cancer by interacting with and triggering YAP phosphorylation." (PMID 35281858, 2022). "Another example is the tumor suppressor lncRNA GAS5 (Growth Arrest-Specific transcript 5), which was found downregulated in gastric cancer via promoter hypermethylation." (PMID 36533073, 2022). "Growth arrest-specific transcript 5 lncRNA (GAS-5) has been known to act as a tumor suppressor and to be notably downregulated in various cancers such as breast, prostate and gastric cancer." (PMID 36077530, 2022). "According to a study on stomach cancer, GAS5 modulates p21 expression and hence maintains G1 phase cell cycle arrest." (PMID 35736636, 2022). "The same GAS5/miR-222 axis was later shown in gastric cancer, papillary thyroid carcinoma, and most recently in B lymphocytic leukemia." (PMID 35054253, 2021).
gastric cancer (continued). "The inhibitory effect of DNA methylation on the expression of the GAS5 gene was demonstrated in other cancers, such as gastric cancer and cervical cancer." (PMID 34202777, 2021). "For example, GAS5/miR-106a-5p/Akt/mTOR (mammalian target of rapamycin) has been reported in gastric cancer." (PMID 33391419, 2021). "LncRNA GAS5 overexpression enhances the killing effect of NK cell on liver cancer through regulating miR-544/RUNX3.Promotes NK cell cytotoxicity against gastric cancer by regulating miR-18a." (PMID 34295338, 2021). "GAS5 can adsorb miR-106a-5p to regulate the Akt/mTOR pathway, thus participating in the development of gastric cancer." (PMID 33777096, 2021). "In gastric cancer, three miRNAs have been reported to relate to GAS5, miR-18a, miR-106a-5p and miR-222." (PMID 33076450, 2020). "Reduced expression of GAS5 was also reported to be concerned with poor patient survival in gastric cancer patient in addition to its involvement in cancer cell proliferation." (PMID 32547314, 2020). "This proposed that allele deletion in GAS5 rs145204276 exerted a protective action in patients with gastric cancer through the modulation of GAS5 transcript." (PMID 32547314, 2020). "A recent study highlighted the fact that GAS5 expression was significantly down-regulated in gastric cancer tissues, and that it was down-regulated in adriamycin-resistant cells." (PMID 33076450, 2020). "In the case of gastric cancer, five miRNAs have been reported to be related to GAS5, miR-222, miR-21, miR-544, miR-135b and miR-34a." (PMID 33076450, 2020). "The expression level of the lncRNA growth arrest specific transcript 5 (GAS5) has been observed to be downregulated in stomach cancer and resulted in decreased p21cip1/waf1 expression and impaired cell cycle arrest at the G1 phase." (PMID 31514410, 2019). "This means that GAS5 can increase the sensitivity of gastric cancer chemotherapy by modulating miR-23a and regulating MT2A expression." (PMID 30606744, 2019). "GAS5 expression is also markedly downregulated in gastric cancer tissues and influences gastric cancer cell proliferation via regulating the expression of E2F1 and P21." (PMID 30853980, 2019). "The discovery that GAS5 can improve the chemosensitivity of gastric cancer is considered to be very important and has good clinical application value, which deserves special attention." (PMID 30606744, 2019). "GAS5 and miR-23a were negatively expressed in gastric cancer cells, and overexpression of GAS5 significantly reduced miR-23a expression." (PMID 30606744, 2019). "They verified that the reduced expression of GAS5 indicates poor prognoses and will lead to gastric cancer cells spreading." (PMID 31572428, 2019). "The researchers said that GAS5 plays an important role in inhibiting the growth of gastric cancer and that knockdown of GAS5 will eliminate the cell cycle arrest of tumor cells." (PMID 30606744, 2019). "For example, GAS5 has been reported to reduce the resistance of pancreatic cancer to gemcitabine and enhance the chemosensitivity of gastric cancer." (PMID 30606744, 2019). "Consistent with our finding, the regulatory effect of GAS5 on YBX1 was identified by a previous study on stomach cancer." (PMID 31534503, 2019). "Taken together, our findings conclude the GAS5 overexpression suppresses tumorigenesis and development of gastric cancer by sponging miR-106a-5p through the Akt/mTOR pathway." (PMID 31182630, 2019). "For example, increased levels of GAS5 can inhibit gastric cancer cell proliferation and induce apoptosis both in vitro and in vivo." (PMID 29642935, 2018). "In gastric cancer cells, GAS5 was reported to inhibit proliferation by upregulation of p21 and suppression of CDK6." (PMID 29029523, 2017).
gastric cancer (continued). "Further literatures reported the potential role of GAS5 in the human T-lymphocytes, renal cell carcinoma, prostate cancer, pancreatic cancer, bladder cancer, non-small-cell lung cancer, gastric cancer, hepatocellular carcinoma, cervical cancer, and so on." (PMID 27863421, 2016). "Then, we detected lncRNA GAS5 expression in 55 paired stomach cancer and normal adjacent tissue specimens." (PMID 25959498, 2015). "Our results revealed that lncRNA GAS5 expression was down-regulated in stomach cancer tissues compared with that in paired normal counterparts." (PMID 25959498, 2015). "Our results indicate that lncRNA GAS5 has lower expression in stomach cancer tissues than in their adjacent normal counterparts." (PMID 25959498, 2015). "The down-regulation of lncRNA growth arrest specific transcript 5 (GAS5) has been reported in several cancers, however, the underlying mechanism of lncRNA GAS5 in stomach cancer is poorly understood." (PMID 25959498, 2015). "In summary, we found that lncRNA GAS5 acts as a tumor suppressor that is down-regulated in stomach cancer." (PMID 25959498, 2015). "Growth inhibition caused by starvation or rapamycin treatment elevated lncRNA GAS5 expression in HGC-27 and SGC-7901 stomach cancer cell lines." (PMID 25959498, 2015). "In order to manipulate GAS5 level in gastric cancer cells, pCDNA3.1-GAS5 vector was transfected into BGC823 and SGC7901 cells." (PMID 24884417, 2014). "We firstly examined GAS5 expression level in 89 paired gastric cancer samples and adjacent, histological normal tissues by qRT-PCR, and normalized to GAPDH." (PMID 24884417, 2014). "To assess the biological role of GAS5 in gastric cancer, we investigated the effect of targeted knockdown or overexpression of GAS5 on cell proliferation and apoptosis." (PMID 24884417, 2014). "Gastric cancer cells transfected with pCDNA3.1 -GAS5 were injected into nude mice to study the effect of GAS5 on tumorigenesis in vivo." (PMID 24884417, 2014). "Our studies were designed to investigate the expression and prognostic significance of GAS5 in patients with gastric cancer." (PMID 24884417, 2014). "Here, we also found P21 was a downstream regulator involved in GAS5-mediated growth arrest in gastric cancer cells." (PMID 24884417, 2014). "Taken together, these results indicate that upregulation of GAS5 suppresses gastric cancer cell proliferation, and induces cell apoptosis in vitro." (PMID 24884417, 2014). "Expression of GAS5 was analyzed in 89 gastric cancer tissues and five gastric cancer cell lines by quantitative reverse-transcription polymerase chain reaction (qRT-PCR)." (PMID 24884417, 2014). "Our studies were designed to investigate the expression, biological role and clinical significance of GAS5 in gastric cancer." (PMID 24884417, 2014). "The results showed that GAS5 expression was significantly decreased in gastric cancer tissues and cell lines." (PMID 24884417, 2014). "In this study, to explore the molecular mechanism by which GAS5 contributes to cell proliferation of gastric cancer, we investigated potential targets which were responsible for cell cycle arrest and cell growth inhibition." (PMID 24884417, 2014). "In this study, we demonstrated that decreased GAS5 expression was a characteristic molecular change in gastric cancer and investigated the effect of altered GAS5 level on the phenotypes of gastric cancer cells in vitro and in vivo." (PMID 24884417, 2014). "One study focusing on stomach cancer identified a mechanism wherein the depletion of GAS5 increased the turnover of transcriptional activator Y-box-binding protein 1 (YBX1) through direct interaction, thereby reducing p21 expression and subsequent G1 phase arrest." (PMID 39941145, 2025). "This novel mechanism of GAS5 suppressing stomach carcinogenesis via the YBX1/p21 pathway serves as a potential target for the development of lncRNA-based therapeutics for the treatment of stomach cancer." (PMID 39941145, 2025).
gastric cancer (continued). "Similarly, NK cells isolated from patients with gastric carcinoma showed downregulation of GAS5 compared to healthy controls." (PMID 40781182, 2025). "In gastric cancer, GAS5 binds to the YBX1 (Y-Box Transcription Factor) protein." (PMID 34202777, 2021). "GAS5 also plays a significant role as a tumor suppressor in gastric cancer." (PMID 33076450, 2020). "Furthermore, lncRNA GAS5 has been observed to be remarkably diminished in gastric cancer tissues, while the ectopic expression of lncRNA GAS5 was verified to suppress gastric cancer cell proliferation and accelerate apoptosis in vitro and in vivo." (PMID 32308561, 2020). "In conclusion, the GAS5/YBX1/p21 pathway controls the proliferation of gastric cancer cells." (PMID 30606744, 2019). "GAS5 has been reported to be aberrantly expressed in some cancers, including lung cancer, cervical cancer, breast cancer and gastric cancer, and plays important roles in cell processes such as proliferation, invasion, migration and apoptosis." (PMID 31182630, 2019). "Collectively, these observations suggest that overexpression of PTENP1-AS and GAS5 in gastric cancer could be abrogating oncogenic activity of miR-21 and confirms that lncRNAs could act as tumor suppressive ceRNAs." (PMID 29719612, 2018). "Gas5 expression is rapidly reduced in some cancers, such as gastric cancer and renal carcinoma." (PMID 29308053, 2018). "In addition, GAS5 expression is further decreased in Adriamycin (ADM)-resistant gastric cancer cells, and increased methylation levels are noted in the GAS5 promoter region." (PMID 29721215, 2018). "GAS5, an lncRNA of approximately 650 bp, has been shown to be significantly down-regulated in gastric cancer tissues compared with corresponding normal tissues, and this decreased expression has been shown to be associated with a large tumour size, advanced pathologic stage, and poorer DFS and OS." (PMID 29137343, 2017). "To explore whether unknown mechanisms are responsible for the ability of lncRNA GAS5 to regulate cell cycle in stomach cancer, we performed an RNA pull-down assay and selected specific protein bands from the GAS5 complex for MS analysis." (PMID 25959498, 2015). "Moreover, the down-regulation of lncRNA GAS5 and of p21 in stomach cancer specimens positively correlated." (PMID 25959498, 2015). "Thus, the lncRNA GAS5/YBX1/p21 pathway is important for controlling cell proliferation in stomach cancer." (PMID 25959498, 2015). "Therefore, we performed this study to explore the function and regulatory mechanism of lncRNA GAS5 in stomach cancer." (PMID 25959498, 2015). "Our findings provide new insight into the function and mechanism of lncRNA GAS5 in stomach cancer." (PMID 25959498, 2015). "Moreover, ectopic expression of GAS5 was demonstrated to decrease gastric cancer cell proliferation and induce apoptosis in vitro and in vivo." (PMID 25889788, 2015). "We further examined whether GAS5 expression level correlated with outcome of gastric cancer patients after gastrectomy." (PMID 24884417, 2014). "Although downregulation of lncRNA GAS5 (Growth Arrest-Specific Transcript) in several cancers has been studied, its role in gastric cancer remains unknown." (PMID 24884417, 2014). "The results showed that GAS5 expression was obviously downregulated in gastric cancer cells, suggesting that a decrease in expression levels may be significant in gastric carcinogenesis." (PMID 24884417, 2014). "Our findings suggest that lncRNA GAS5 may represent a novel indicator of poor prognosis in gastric cancer and may be a potential therapeutic target for diagnosis and gene therapy." (PMID 24884417, 2014).
gastric cancer (continued). "Our study presents that GAS5 is significantly downregulated in gastric cancer tissues and may represent a new marker of poor prognosis and a potential therapeutic target for gastric cancer intervention." (PMID 24884417, 2014). "According to the median ratio of relative GAS5 expression (0.38) in tumor tissues, the 89 gastric cancer patients were classified into two groups: relative high-GAS5 group (n = 45, GAS5 expression ratio ≥ median ratio) and relative low-GAS5 group (n = 44, GAS5 expression ratio ≤ median ratio)." (PMID 24884417, 2014). "GAS5 expression was retrospectively analyzed in 89 patients with gastric carcinoma." (PMID 24884417, 2014). "In other type of cancer, although the GAS5 SNP rs145204276 is related to a lower incidence of tumor progression in gastric cancer and serves as a protector, the existence of GAS5 SNP rs145204276 may contribute to a worse tumor stage and size in certain subjects with oral cancer." (PMID 36011604, 2022). "In addition, overexpression of GAS5 could inhibit gastric cancer cell proliferation and induce apoptosis both in vitro and in vivo." (PMID 27620004, 2016). "In 55 paired stomach cancer and normal adjacent specimens, the p21 mRNA level was significantly down-regulated in 72.7% of cancer tissues compared with paired normal tissues, which was positively correlated with decreased lncRNA GAS5 expression in tissue specimens." (PMID 25959498, 2015). "However, few reports have examined the role of lncRNA GAS5 in stomach cancer." (PMID 25959498, 2015). "Finally, we found that GAS5 could influence gastric cancer cells proliferation, partly via regulating E2F1 and P21 expression." (PMID 24884417, 2014). "Moreover, ectopic expression of GAS5 was demonstrated to decrease gastric cancer cell proliferation and induce apoptosis in vitro and in vivo, while downregulation of endogenous GAS5 could promote cell proliferation." (PMID 24884417, 2014). "Moreover, ectopic expression of GAS5 was demonstrated to decrease gastric cancer cell proliferation and induce apoptosis, while downregulation of endogenous GAS5 could promote cell proliferation in vitro and in vivo." (PMID 24884417, 2014). "Taken together, these findings indicate that GAS5 could function as a tumor suppressor via regulating cell growth and apoptosis, and may be useful in the development of novel prognostic or progression markers for gastric cancer." (PMID 24884417, 2014). "It is worth noting that some lncRNAs, such as GAS5 and ADAMTS9-AS2, were found to have inhibitory effects on the proliferation of drug-resistant gastric cancer cell lines in this review." (PMID 38927012, 2024). "The lncRNA GAS5 acts as a tumor suppressor and is downregulated in gastric cancer (GC)." (PMID 36316351, 2022). "It has been reported that HOTAIR, ANRIL, GAPLINC, GHET1, H19, GAS5, and FENDRR, etc., play roles in the malignant progression of gastric cancer." (PMID 33744848, 2021). "GAS5 and MALAT1 modulate chemo resistance in gastric cancers and glioblastoma multiforma cells, respectively." (PMID 31141943, 2019). "lncRNA GAS5 down-regulation reduced the YBX1 protein level, which decreased YBX1-transactivated p21 expression and abolished G1 phase cell cycle arrest in stomach cancer." (PMID 25959498, 2015). "In two stomach cancer cell lines, i.e., HGC-27 and SGC-7901, we also found that lncRNA GAS5 was up-regulated in an obvious time-dependent manner when starved for 6 h and 18 h." (PMID 25959498, 2015). "Multivariate analysis revealed that GAS5 expression and TNM stage were independent prognostic markers for gastric cancer." (PMID 24884417, 2014). "The GAS5/miR-222 axis also regulates the PTEN/AKT/mTOR pathway to suppress the progression of other cancers, such as papillary thyroid carcinoma, human B lymphocytic leukemia, and gastric cancer." (PMID 39941145, 2025).